NSUN6 (NOP2/Sun RNA methyltransferase 6)
Diseases named in the same sentence as NSUN6 in open-access papers (continued):
Sharing a sentence is not in itself a finding about the gene and the disease.
cervical cancer (3 papers, 2024 to 2025). A primary or metastatic malignant neoplasm involving the cervix. "Conversely, NSUN6 overexpression has been associated with radiation resistance and poor prognosis in cervical cancer." (PMID 41462962, 2025). "Functionally, higher NSUN6 expression was associated with radioresistance in the 3D PDO model of cervical cancer." (PMID 38970106, 2024). "The integration of m5C-seq, mRNA-seq, and functional validation identified NDRG1 as a downstream target gene of NSUN6 in cervical cancer." (PMID 41462962, 2025). "Abnormal m5C high methylation and NSUN6 overexpression drive the radiotherapy resistance of cervical cancer, where elevated NSUN6 expression promotes radiation resistance by activating the NSUN6–ALYREF–m5C–NDRG1 pathway." (PMID 41462962, 2025). "The abundance of m5C modification was higher in radiation-resistant cervical cancer samples, and the low NSUN6 expression in cervical cancer indicated sensitivity to radiotherapy and better prognosis." (PMID 41462962, 2025). "Mechanistically, the NSUN6-m5C-NDRG1 axis promotes radioresistance of cervical cancer via increased DNA repair." (PMID 38970106, 2024). "In the study, we demonstrated that the m5C level is significantly increased due to the upregulation of methyltransferase NSUN6 in radioresistant cervical cancer samples." (PMID 38970106, 2024). "NSUN6 overexpression was clinically correlated with radioresistance and poor prognosis in cervical cancer." (PMID 38970106, 2024). "Aberrant m5C hypermethylation and NSUN6 overexpression drive resistance to radiotherapy in cervical cancer." (PMID 38970106, 2024). "The findings suggested that reducing NSUN6 expression can enhance cervical cancer radiosensitivity in vitro." (PMID 38970106, 2024). "Collectively, our data provided novel evidence that NSUN6/ALYREF-mediated m5C modification maintained the stability of NDRG1 mRNA in cervical cancer." (PMID 38970106, 2024). "By detecting NSUN6 expression levels in cervical cancer samples by IHC, we can prospectively predict the radiosensitivity of the corresponding patients." (PMID 38970106, 2024). "As expected, cervical cancer organoids with low NSUN6 expression were more sensitive to IR than those with high NSUN6 expression." (PMID 38970106, 2024). "In summary, we provided compelling in vitro and in vivo evidence demonstrating that m5C and NSUN6 can regulate the radiosensitivity of cervical cancer via the regulation of NDRG1." (PMID 38970106, 2024). "Results of clone formation assay and apoptosis assay indicated that NSUN6 knockdown decreased the IR dose threshold for cervical cancer cell death." (PMID 38970106, 2024). "The low expression of NSUN6 in cervical cancer indicates sensitivity to radiotherapy and a better prognosis." (PMID 38970106, 2024). "Elevated NSUN6 expression promotes radioresistance in cervical cancer by activating the NSUN6/ALYREF-m5C-NDRG1 pathway." (PMID 38970106, 2024). "To elucidate the m5C-modified genes mediated by NSUN6 and to further elucidate the molecular mechanisms by which NSUN6 regulates radiosensitivity in cervical cancer, we performed mRNA and m5C-MeRIP sequencing in SiHa cells with or without NSUN6 knockdown." (PMID 38970106, 2024). "3D bioprinted patient-derived organoid (PDO) and cell-derived xenograft model (CDX) further verified that elevated NSUN6 promotes resistance to radiotherapy in cervical cancer." (PMID 38970106, 2024). "Thus, our findings illustrate a regulatory mechanism of RNA m5C-mediated radioresistance and provide a therapeutic rationale for targeting the NSUN6/ALYREF-m5C-NDRG1 signaling axis in cervical cancer." (PMID 38970106, 2024). "Moreover, NSUN6 expression significantly increases in radioresistant samples and is correlated with poor prognosis in patients with cervical cancer." (PMID 38970106, 2024). "Moreover, overexpression of NSUN6, an m5C methyltransferase, was observed in radioresistant cervical cancer samples." (PMID 38970106, 2024).
cervical cancer (continued). "Patients with high NSUN6 expression in cervical cancer had significantly worse OS and RFS." (PMID 38970106, 2024). "In addition, we found that downregulating NSUN6 increased the sensitivity of cervical cancer cells to cisplatin/Olaparib." (PMID 38970106, 2024). "To determine whether inhibiting NSUN6 could sensitize cervical cancer to radiotherapy, we established stable NSUN6-knockdown cervical cancer cells (SiHa and Me-180) for loss-of-function studies." (PMID 38970106, 2024). "Nevertheless, whether and how m5C modifications and NSUN6 play roles in cervical cancer radiosensitivity remain unclear." (PMID 38970106, 2024). "Our data and published results suggested that m5C and NSUN6 may drive radioresistance in cervical cancer, but the exact mechanism requires further exploration." (PMID 38970106, 2024). "Therefore, NSUN6 may represent a potential predictor and therapeutic target for cervical cancer." (PMID 38970106, 2024). "By joint analysis of the expression of NSUN6 and NDRG1, we found that cases with high expression of both NSUN6 and NDRG1 tended to exhibit a worse prognosis in cervical cancer." (PMID 38970106, 2024). "Finally, we characterized the relationships between NSUN6/NDRG1 expression and clinical prognosis in cervical cancer by performing IHC in 205 advanced cervical cancer tissues." (PMID 38970106, 2024).
hepatocellular carcinoma (3 papers, 2022 to 2025). A malignant tumor that arises from hepatocytes. "In hepatocellular carcinoma (HCC), the methyltransferase NSUN6 catalyzes m5C modification of BMPER mRNA, enhancing its stability and elevating BMPER protein expression." (PMID 40589169, 2025).
liver cancer (3 papers, 2020 to 2022). An epithelial or non-epithelial malignant neoplasm that arises from the liver. "Among them, the P value of the NSUN5 and ALYREF genes in colorectal cancer, liver cancer, and GC is less than 0.05, and the NSUN6 gene also has significant differences in colorectal cancer, liver cancer, and PC." (PMID 33365328, 2020). "In line with our finding that Nsun6 was higher expressed in normal liver than liver tumours, over-expression of NSUN6 has recently been shown to inhibit cell proliferation of liver cancer cells." (PMID 33330931, 2021).
ovary cancer (3 papers, 2022 to 2025). "On the other hand, NSUN6, a methyltransferase, is involved in RNA m5C modification and has a suppressive effect on testis, thyroid and ovary cancers." (PMID 40008496, 2025). "In contrast, RNA m5C modification mediated by the methyltransferase NSUN6 suppresses testis, thyroid and ovary cancers." (PMID 37325635, 2023). "Among these results, we only found a significant reduction of NSUN6 mRNA in ovarian cancer." (PMID 35280737, 2022). "In addition, the expression of NSUN6 was not correlated with the prognosis of ovarian cancer analyzed by Kaplan–Meier Plotter." (PMID 35280737, 2022).
colon cancer (2 papers, 2023 to 2025). "Immunohistochemistry has demonstrated increased NSUN6 expression in colon cancer, where high NSUN6 levels were associated with shorter OS." (PMID 41462962, 2025). "In clinical practice, high NSUN6 expression is significantly associated with shorter DFS and OS in patients with colon cancer." (PMID 41462962, 2025). "Mechanistically, NSUN6 promotes cell cycle progression and cell proliferation of colon cancer through the oncogene METTL3." (PMID 41462962, 2025). "NSUN6 is upregulated in both colon cancer tissues and cells." (PMID 41462962, 2025). "NSUN6 upregulates the expression of the oncogene METTL3 and catalyzes its m5C modification in colon cancer cells." (PMID 41462962, 2025).
colorectal cancer (2 papers, 2020 to 2022). A primary or metastatic malignant neoplasm that affects the colon or rectum. "NSUN6 expression could predict prognosis in both breast and colorectal cancer." (PMID 36060802, 2022).
cutaneous melanoma (2 papers, 2022). A primary melanoma arising from atypical melanocytes in the skin. "Several m5C-regulators are associated with overall survival prognosis in cutaneous melanoma (DNMT2, NSUN1, NSUN3, NSUN6 and YBX1)." (PMID 36060802, 2022). "In cutaneous melanoma (CM), DNMT2, NSUN3, NSUN6, YBX1, and NOP2 are differentially expressed and used to calculate risk scores in patients." (PMID 35562754, 2022).
melanoma (2 papers, 2022). A malignant, usually aggressive tumor composed of atypical, neoplastic melanocytes. "In particular, low NSUN6 expression was shown to correlate with melanoma progression." (PMID 36060802, 2022). "JQ1 was characterized by induction of inhibitory relationship linking regulators of inflammation (IFNG, IL17A, TGFB2), melanoma biological behavior (EGFR, WNT3A, TEADs, MRTFB), cell-cell interaction (CD44, CCN2), YAP pathway (LLGL2, NSUN6) and main transcriptional regulators (FOS, JUN, FOXM1)." (PMID 36397155, 2022).
osteosarcoma (2 papers, 2025). A usually aggressive malignant bone-forming mesenchymal neoplasm, predominantly affecting adolescents and young adults. "In osteosarcoma, decreased NSUN6 expression reduced m5C modifications on PEX1 and PEX3 mRNA, leading to PEX1 and PEX3 instability by losing the binding of the m5C recognition protein YBX1." (PMID 41462962, 2025). "Conversely, in osteosarcoma, NSUN6 is upregulated and correlates with poor prognosis, highlighting its context‐dependent role in cancer biology." (PMID 40561176, 2025). "NSUN6 promoted osteosarcoma progression through EEF1A2 expression and inhibiting the AKT–mTOR signaling pathway via m5C methylation." (PMID 41462962, 2025). "Bioinformatics analysis and RIP and MeRIP assays identified and validated EEF1A2 as a potential target of NSUN6 in osteosarcoma." (PMID 41462962, 2025). "NSUN6 is upregulated in osteosarcoma, and higher NSUN6 expression indicates poor prognosis." (PMID 41462962, 2025). "Furthermore, NSUN6 led to osteosarcoma cell proliferation, migration, and invasion." (PMID 41462962, 2025). "The NSUN6–m5C–YBX1–PEXs signaling axis regulates peroxisome biogenesis, ROS accumulation, and cisplatin sensitivity in osteosarcoma." (PMID 41462962, 2025).
autosomal-recessive intellectual disability (1 paper, 2024). "Loss-of-function mutations in NOP2/Sun RNA MT2 and MT6 (NSUN2 and NSUN6, respectively) have been identified as the cause of autosomal-recessive intellectual disability (ID) in humans." (PMID 38550277, 2024).
bladder cancer (1 paper, 2023). "Immunohistochemistry of bladder cancer samples also demonstrated that HDAC10 expression was also significantly elevated in NSUN6‐high samples." (PMID 37408139, 2023).
colorectal tumour (1 paper, 2024). "There were no obvious differences in NSUN6, NSUN7 and TRDMT1 expression between the colorectal tumour tissues and adjacent normal tissues." (PMID 38468490, 2024).
depression (1 paper, 2025). "NOP2 and NSUN6 are both RNA methyltransferases that affect the cell cycle and proliferation activities and show high levels in carcinoma and sepsis and even provide new potential therapeutic approaches for preventing depression." (PMID 40405297, 2025).
head and neck squamous cell carcinoma (1 paper, 2021). A squamous cell carcinoma that arises from any of the following anatomic sites: lip and oral cavity, nasal cavity, paranasal sinuses, pharynx, larynx, and salivary glands. "NSUN4, NSUN5, NSUN6 and NSUN7 are associated with cancer development in HCC, head and neck squamous cell carcinoma (HNSCC), pancreatic cancer and glioma 29, 114-116." (PMID 34512153, 2021).
Hutchinson-Gilford progeria syndrome (1 paper, 2025). "Additionally, the expression levels of NSUN2 and NSUN6 were significantly decreased in a cellular model of Hutchinson-Gilford Progeria Syndrome (HGPS)." (PMID 40309035, 2025).
kidney cancer (1 paper, 2022). Primary or metastatic malignant neoplasm involving the kidney. "In contrast, it is upregulated in tumors originating from tissues that have low NSUN6 expression, such as that in hematologic tumor and kidney cancer." (PMID 35309925, 2022).
ovarian serous cystadenocarcinoma (1 paper, 2022). A malignant serous cystic epithelial neoplasm arising from the ovary. "Likewise, FDX1 expression was positively correlated with NSUN6 levels in 10 tumors, except for GBM, KIRC, KIRP, brain lower grade glioma (LGG), and ovarian serous cystadenocarcinoma (OV)." (PMID 36210836, 2022).
renal cell carcinoma (1 paper, 2023). "NSUN4 and NSUN6 as model genes participate in the prognostic model of renal cell carcinoma." (PMID 37934565, 2023).
rheumatoid arthritis (1 paper, 2025). A chronic, systemic autoimmune disorder characterized by inflammation in the synovial membranes and articular surfaces. "RNA-Seq and RT-qPCR validation of peripheral blood samples revealed that NSUN6 is a key gene in rheumatoid arthritis-associated interstitial lung disease, where its expression was significantly lower than that of rheumatoid arthritis-only patients." (PMID 41462962, 2025).
tumor (31 papers, 2020 to 2025). "In the present study, NSUN6 was lowly expressed in HCC and associated with poor diagnosis, while NSUN6 overexpression suppressed cell proliferation, migration, and tumor growth." (PMID 40589169, 2025). "This NSUN6‐BMPER axis suppresses HCC progression by inhibiting tumor cell proliferation/migration while correlating with improved patient prognosis, establishing RNA epigenetic regulation as a key inhibitory mechanism in liver cancer." (PMID 40589169, 2025). "The results showed that the tumor volume and weight were significantly lower in the NSUN6 overexpression group compared to the control group." (PMID 40589169, 2025). "Among these genes, NSUN6 was identified as a key protective factor, with tumor‐suppressive potential validated by both computational and experimental approaches." (PMID 40561176, 2025). "The mechanistic and functional diversity of NSUN6-mediated tumor radioresistance operates through the m5C-NDRG1 axis." (PMID 40823093, 2025). "Taken together, these results suggested that NSUN6 up‐regulation acts as a tumor suppressor by inhibiting the proliferation and migration of HCC cells." (PMID 40589169, 2025). "In PDAC, low NSUN6 expression is associated with enhanced cancer cell proliferation and decreased sensitivity to chemotherapy, whereas restoring NSUN6 activity inhibits tumor cell proliferation and reduces invasiveness, improving patient outcomes." (PMID 40114967, 2025). "NSUN6 plays a critical role in CRC and PDAC; in CRC, higher NSUN6 expression is linked to advanced tumor stages and lower survival rates, while in PDAC, reduced NSUN6 expression negatively correlates with prognostic markers like T stage and Ki67 positivity." (PMID 40114967, 2025). "NSUN6 is one of the m5C methyltransferases, which was found to play a critical role in cell proliferation and tumor progression, however its specific effect on HF still needs further exploration." (PMID 40405297, 2025). "Mechanistically, in TNBC, both NSUN2 and NSUN6 play critical roles in tumourigenicity and the tumour immune microenvironment." (PMID 40008496, 2025). "By analyzing the multi-IF images, we found that organoids and paired primary tumor tissues exhibited similar staining patterns for NSUN6 and Ki-67." (PMID 38970106, 2024). "NSUN6, one of the m5C methyltransferases, plays a critical role in cell proliferation and tumor progression." (PMID 38970106, 2024). "One possible explanation of the controversial role of NSUN6 in different types of cancers is that NSUN6 expression level in different immune cells within the TME differs based on the tumor context." (PMID 37325635, 2023). "NSUN2, NSUN5, NSUN6, DNMT3A, DNMT3B, ALYREF, and TET3 acted as tumor risk factors, and overexpression of these genes led to a poorer prognosis for ccRCC patients." (PMID 36661693, 2022). "In clear cell renal cell carcinoma (ccRCC), the mRNA levels of NOP2 and NSUN4 are higher in tumor tissues than in normal tissues, whereas the mRNA levels of NSUN6 and m5C eraser TET2 are lower." (PMID 35562754, 2022). "Conversely, NSUN6 presented tumor-suppressing characteristics, with higher gene expression levels related to favorable prognosis." (PMID 35252205, 2022). "When we analysed tumours derived from tissues with high or low Nsun6-expression, we found Nsun6 mRNA levels to be down-regulated in tumours, but only when derived from high Nsun6-expressing tissues." (PMID 33330931, 2021). "While NSUN6 was dispensable for mouse embryonic development, it was down-regulated in human tumours and high expression of NSUN6 indicated better patient outcome of certain cancer types." (PMID 33330931, 2021). "Our findings pave the path toward mechanistic dissection of the physiological importance of NSUN6, such as its roles in cell proliferation and tumor progression." (PMID 34691665, 2021). "For tumor grade, the expression of m5C regulators increased from G1 to G3 except NSUN6, which showed an opposite trend of expression." (PMID 33365328, 2020).